GATA2 (GATA binding protein 2)
Diseases named in the same sentence as GATA2 in open-access papers (continued):
Sharing a sentence is not in itself a finding about the gene and the disease.
age-related macular degeneration (1 paper, 2025). Age-related loss of vision in the central portion of the retina (macula), secondary to retinal degeneration. "further demonstrated that metformin modulates the gut microbiome to increase Bifidobacterium and Akkermansia abundance, downregulate proangiogenic genes (Tie1, Pgf, and Gata2), and attenuate the development of age-related macular degeneration (AMD)." (PMID 41278472, 2025).
allergic asthma (1 paper, 2025). A asthma with a basis in a pathological type I hypersensitivity reaction. "For instance, GATA2, TET2, and TWIST1 are enriched for more than one gene co-occurrence pair and are known to influence allergic asthma (63, –65)." (PMID 40504147, 2025).
aneurysm (1 paper, 2022). Bulging or ballooning in an area of an artery secondary to arterial wall weakening. "(ii) We observed two novel clinical features multiple aneurysms of small vessels (n = 1) and early graying (n = 1) that could be associated with GATA2 deficiency." (PMID 34893945, 2022).
astrocytoma (1 paper, 2025). "This study investigates a novel genetic mutation, p.Arg396Trp, in the GATA2 gene, identified in an IDH-mutant astrocytoma patient through whole-genome sequencing." (PMID 41154393, 2025).
Central hypothyroidism (1 paper, 2021). A type of hypothyroidism due to an insufficient stimulation of an otherwise normal thyroid gland. "Genetic testing of GATA2 mutations in patients with central hypothyroidism is an important issue that needs to be addressed further." (PMID 34576178, 2021). "Because reduced pituitary TSH reserve and impaired thyrotropic stimulation by TRH are included in the pathophysiology of central hypothyroidism in humans, mutated GATA2 may contribute to develop this disorder." (PMID 34576178, 2021).
cerebrovascular diseases (1 paper, 2024). "The TFs-gene regulatory networks identified the core TFs including PPARG, FOXC1 and GATA2, known for their roles in the inflammation regulation in the cerebrovascular diseases." (PMID 39469068, 2024).
cholesterol pneumonia (1 paper, 2015). "Those two patients had the typical phenotype of GATA2 deficiency, one of whom additionally showed a previously undescribed feature – a cholesterol pneumonia." (PMID 26264606, 2015).
cryptogenic organizing pneumonia (1 paper, 2025). Cryptogenic organizing pneumonia (COP) is a form of idiopathic interstitial pneumonia characterized pathologically by organizing pneumonia (OP) that presents with non-specific flu-like symptoms, as well as cough and dyspnea and where no etiological agent is found. "This case report describes cryptogenic organizing pneumonia occurring in a patient with GATA2 deficiency, an observation that has not been well reported but cannot be assumed to represent a causal relationship." (PMID 41438140, 2025).
degenerative joint disease (1 paper, 2020). "We identified osteopenia and degenerative joint disease in several patients with GATA2 deficiency, predominantly in the post-transplant period." (PMID 32433473, 2020).
depression (1 paper, 2021). "Additionally, four genes HELZ2, PTPRN2, GATA2, and ZNF624 were differentially expressed between depression cases and health controls." (PMID 34341332, 2021).
Encephalopathy (1 paper, 2025). Encephalopathy is a term that means brain disease, damage, or malfunction. "GATA2 is also expressed in neural tissues, with studies reporting unique complications like peripheral polyneuropathy, noninfectious encephalopathy or unexplained behavioral changes, mainly as neurotoxicity after HSCT." (PMID 40299403, 2025).
endometrial disorder (1 paper, 2024). A non-neoplastic or neoplastic disorder that affects the endometrium. "Our findings support a model whereby GATA2 dysregulation is a feature of multiple endometrial disorders which can be routinely detected by IHC on patient tissue biopsies." (PMID 39443360, 2024).
endometrial polyp (1 paper, 2024). A benign nodular lesion protruding above the surface of the endometrium. "We subsequently evaluated endometrial GATA2 expression in the setting of common benign endometrial conditions associated with abnormal PGR activity including hormone-treated patients, peri/post-menopausal patients who have inactive endometrium, and in the setting of endometrial polyps." (PMID 39443360, 2024).
erythroleukemia (1 paper, 2015). Acute erythroid leukemia characterised by the presence of at least 50% erythroid precursors and at least 20% myeloblasts in the bone marrow. "Here, we conducted high-throughput small-interfering-RNA (siRNA) library screening and showed that YN-1, a human erythroleukemia cell line, expressed high levels of GATA-2 following the activation of the hematopoietic-specific 1S promoter." (PMID 26325290, 2015).
fibromyalgia (1 paper, 2025). A chronic disorder of unknown etiology characterized by pain, stiffness, and tenderness in the muscles of neck, shoulders, back, hips, arms, and legs. "Although differential expression of 421 genes has been documented in the development of fibromyalgia (e.g., HDC, GATA2, and APBB2), genome-wide expression profiling in patients with fibromyalgia did not reveal any alterations within the ECS." (PMID 40699629, 2025).
genital warts (1 paper, 2021). "To date, mainly case reports or series were reported, showing that GATA binding protein 2 (GATA2) and CXC motif chemokine receptor type 4 (CXCR4) deficiencies are associated with genital warts." (PMID 34868076, 2021).
graft versus host disease (1 paper, 2025). An immune system disorder that occurs after allogeneic hematopoietic stem cell transplant and is a reaction of donor immune cells against host tissues. "GATA2 patients undergoing HSCT experience high rates of graft versus host disease (GvHD) as well as unique neurological, thrombotic, and infectious complications." (PMID 40299403, 2025).
head and neck squamous cell carcinoma (1 paper, 2025). A squamous cell carcinoma that arises from any of the following anatomic sites: lip and oral cavity, nasal cavity, paranasal sinuses, pharynx, larynx, and salivary glands. "A unique case of an aggressive head and neck squamous cell carcinoma that was ultimately discovered to be in the setting of GATA2 deficiency is reported." (PMID 39981594, 2025).
human papillomavirus infection (1 paper, 2025). "Patient 2 was suspected of GATA2 deficiency based on skin symptoms suggestive of human papillomavirus infection and monocyte/dendritic cell deficiency." (PMID 40821825, 2025).
idiopathic scoliosis (1 paper, 2016). A scoliosis with no known cause. "However, at present, considering that the GATA2 minimal promoter and an lbx1b enhancer could drive lbx1b expression in neural tissue later in development, we cannot exclude the possibility that lbx1b expression after convergent extension causes idiopathic scoliosis." (PMID 26820155, 2016).
Infertility (1 paper, 2023). "Mice with uterine-specific ablation of GATA2 displayed inadequate endometrial decidualization, implantation failure, and infertility." (PMID 37901230, 2023).
influenza (1 paper, 2021). An acute viral infection of the respiratory tract, occurring in isolated cases, in epidemics, or in pandemics; it is caused by serologically different strains of viruses (influenzaviruses) designated A, B, and C, has a 3-day incubation period, and usually lasts for 3 to 10 days. "Likewise, patients with GATA2 deficiency, who are prone to critical influenza, lack pDCs, but these patients also lack many other blood cell subsets." (PMID 34413140, 2021).
interstitial lung disease (1 paper, 2025). A diverse group of lung diseases that affect the lung parenchyma. "Here, we describe a case of GATA2 deficiency with early‐onset and progressive interstitial lung disease." (PMID 40264496, 2025). "We concluded that this patient's interstitial lung disease was likely caused by GATA2 deficiency." (PMID 40264496, 2025). "Only one case of interstitial lung disease complicating GATA2 deficiency has been reported." (PMID 40264496, 2025). "Interstitial lung disease is a rare manifestation of GATA2 deficiency." (PMID 40264496, 2025). "Early‐onset interstitial lung disease may be a rare phenotype of GATA2 deficiency." (PMID 40264496, 2025).
ischemia (1 paper, 2022). A hypoperfusion of the BLOOD through an organ or tissue caused by a PATHOLOGIC CONSTRICTION or obstruction of its BLOOD VESSELS, or an absence of BLOOD CIRCULATION. "Sixty days after hHTX, GATA2 expression was significantly downregulated in grafts subjected to 12 h of ischemia, but this effect was reversed when donors had received S-NO-HSA (−6.00 ± 0.45 vs. −7.188 ± 0.5; 12 h-S-NO-HSA-hHTX vs. 12 h-control-hHTX: p = 0.0008; normalized expression to ACTB)." (PMID 35497886, 2022).
kidney (1 paper, 2025). "In 2017, we were the first to report that GATA binding protein 2 (GATA2) promotes kidney inflammation." (PMID 40516868, 2025).
kidney damage (1 paper, 2025). "By inhibiting GATA2, the expression of inflammatory factors can be reduced, and kidney damage can be significantly alleviated." (PMID 40078458, 2025).
kidney inflammation (1 paper, 2025). "Induction of GATA2 increased both mRNA expression and chromatin accessibility in genes associated with kidney inflammation." (PMID 40516868, 2025). "Inducible gene systems offer a straightforward approach to directly assess whether GATA2 comprehensively regulates transcription and chromatin accessibility in genes associated with kidney inflammation." (PMID 40516868, 2025).
leishmaniasis (1 paper, 2022). Infectious disease that is transmitted through the bite of hematophagous female phlebotomine sand flies. "In T. scripta elegans, GATA2-high-basophils were related to pathways involved in regulating T cells, cancer, leishmaniasis, apoptosis, and mitophagy, whereas GATA2-low-basophils were related to pathways in cancer, T cell differentiation, and defense against parasites." (PMID 36552787, 2022).
liver cirrhosis (1 paper, 2017). "In the present study, we identify a liver cirrhosis TF—miRNA—mRNA network containing 49 TFs, many of which have been previously implicated in liver disease (e.g. ETS1, FOS, FOXP3, FOXA2, and GATA2)." (PMID 28355233, 2017).
liver fibrosis (1 paper, 2017). "HOXA7, mostly mutated in the high liver fibrosis group, was reported to promote metastasis of HCC with activation of Snail, while decreased expression of GATA2 was correlated with poor prognosis of HCC." (PMID 29212479, 2017).
mantle zone lymphoma (1 paper, 2020). "In contrast, virus-positive MCC was identified in a patient with mantle zone lymphoma having been treated with Rituximab for 3 years and another with germline mutations in NF1 and GATA2." (PMID 32188490, 2020).
mastocytoma (1 paper, 2025). A localized tumor composed of sheets of mast cells without atypia. "NIH3T3 cells (a murine embryo fibroblast cell line) exhibited moderate Gata2 expression, while P815 mouse mastocytoma cell lines exhibited high Gata2 expression." (PMID 40516868, 2025).
Merkel Cell Carcinoma (1 paper, 2024). "Molecular analysis revealed a germline GATA2 S447R variant, not reported from the previous reported case, suggesting a potential association with Merkel cell carcinoma." (PMID 39614632, 2024).
mesenchymal tumors (1 paper, 2025). "In contrast to GATA2, which primarily acts as an upstream repressor of adipogenesis, GATA3 and GATA4 are dynamically modulated during differentiation and have been implicated in the transcriptional plasticity of mesenchymal tumors." (PMID 41303462, 2025).
metastatic prostate carcinoma (1 paper, 2014). A carcinoma that arises from the prostate gland and has spread to other anatomic sites. "If confirmed, the GATA2 gene would represent a new and important target for therapy of metastatic prostate cancer." (PMID 24448395, 2014). "Examination of a large scale, integrated cancer genomic dataset of the MSKCC Prostate Oncogenome Project indicated that GATA2 gene expression was significantly elevated in metastatic prostate cancer samples." (PMID 24448395, 2014). "However, a role for GATA2 in the development of metastatic prostate cancer has not been reported." (PMID 24448395, 2014).
mild cognitive impairment (1 paper, 2023). "A meta-analysis suggested GATA2 as a common TF regulating mild cognitive impairment and AD." (PMID 37736681, 2023).
MIRAGE syndrome (1 paper, 2018). An autosomal dominant condition caused by mutation(s) in the SAMD9 gene, encoding sterile alpha motif domain-containing protein 9A. "This idea is based on the observation that like in GATA2 deficiency syndrome, the competitiveness of HSC is greatly reduced in ATXPC and MIRAGE syndrome and monocytes and NK cells are also reduced in number and possibly function." (PMID 29535429, 2018).
nasopharyngeal carcinoma (1 paper, 2020). A carcinoma arising from the nasopharyngeal epithelium. "In hematopietic stem cells, for example, TWIST1 binds to the promoter of Gata2 and induces its transcription, while in nasopharyngeal carcinoma cells, GATA2 induces EMT by binding to the promoter of Twist1 and activating its expression." (PMID 32226439, 2020).
oral cancer (1 paper, 2023). "We report the molecular docking analysis for oral cancer drug, Imiquimod with TGF-β signaling pathway targets such as Smad2, GATA2, and MAFG which are mainly plays a crucial role in regulation of Epithelial Mesenchymal Transition(EMT) in cancer cells." (PMID 37822834, 2023).
oral disease (1 paper, 2020). "Good oral hygiene and regular dental visits are recommended, especially for HPV-related oral disease surveillance, as well as periodic gynecological visits for women with GATA2 deficiency." (PMID 33066218, 2020).
Osteopenia (1 paper, 2020). Osteopenia is a term to define bone density that is not normal but also not as low as osteoporosis. "Her brother, a 22-year-old (6.I.2) with GATA2 deficiency and osteopenia refractory to calcium and vitamin D supplementation also had PPP and increased range of motion in his shoulders bilaterally." (PMID 32433473, 2020). "To further evaluate osteopenia, we reviewed available DEXA scans for all patients with GATA2 deficiency." (PMID 32433473, 2020).
pediatric cancers (1 paper, 2022). "GATA2 variants carry a known predisposition to pediatric cancers due to the disruption of the maintenance of hematopoietic stem cells." (PMID 36497424, 2022).
preeclampsia (1 paper, 2019). Preeclampsia is a hypertensive disorder of pregnancy that is characterized by new-onset hypertension with proteinuria presenting after 20 weeks of gestation, and depending on mild or severe forms may initially present with severe headache, visual disturbances, and hyperreflexia. "Therefore, it appears that preeclampsia is associated with decreased circulating GATA2 mRNA levels preceding clinical diagnosis." (PMID 30659233, 2019). "We measured GATA2 mRNA in 34 placentas from women with preterm preeclampsia, compared to 12 controls (from preterm deliveries where the women remained normotensive and did not develop preeclampsia)." (PMID 30659233, 2019). "Circulating GATA2 mRNA concentrations were significantly reduced, by ~35% among participants with preeclampsia, compared to controls (p = 0.002)." (PMID 30659233, 2019). "This study provides the first data to demonstrate that circulating GATA2 mRNA is significantly reduced, not only in established preeclampsia, but also as early as 10–12 weeks preceding the clinical diagnosis of the disease." (PMID 30659233, 2019). "We have confirmed that this is also likely in preeclampsia in our functional experiments, demonstrating that placental factors or TNFα significantly reduced endothelial GATA2 coincident with increased VCAM-1 expression." (PMID 30659233, 2019). "We initially measured circulating GATA2 mRNA in whole blood among 34 women with established early onset preeclampsia (delivered <34 weeks’ gestation), compared with 21 normotensive healthy pregnancies who subsequently delivered at term." (PMID 30659233, 2019). "Circulating GATA2 mRNA was significantly reduced in women destined to develop preeclampsia at 36 weeks’ gestation, compared to controls (p = 0.015), with an area under the receiver operating characteristic (ROC) curve (AUC) of 0.63." (PMID 30659233, 2019). "Using case-control groups selected from a large prospective cohort, whole blood circulating GATA2 mRNA at both 28 and 36 weeks’ gestation was significantly reduced prior to the clinical diagnosis of preeclampsia (p = 0.012, p = 0.015 respectively)." (PMID 30659233, 2019). "Circulating GATA2 mRNA is decreased in women with established preeclampsia and decreased up to 12 weeks preceding onset of disease." (PMID 30659233, 2019). "Whole blood circulating GATA2 mRNA and miR126 expression were significantly decreased in women with established early-onset preeclampsia compared to gestation-matched controls (p = 0.002, p < 0.0001, respectively)." (PMID 30659233, 2019). "It provides functional evidence to suggest that similar changes may result in the reduced circulating GATA2 observed in the circulation of women preceding, or with established preeclampsia." (PMID 30659233, 2019). "Indeed, we found significantly decreased circulating GATA2 mRNA in both established early-onset preeclampsia and preceding diagnosis of late-onset preeclampsia." (PMID 30659233, 2019). "Free circulating GATA2 mRNA level could be combined with placental biomarkers or other endothelial biomarkers to improve the sensitivity and specificity in predicting preeclampsia." (PMID 30659233, 2019). "Given circulating GATA2 mRNA levels were changed among women with established preeclampsia, we next examined whether levels were differentially expressed prior to the development of late-onset disease." (PMID 30659233, 2019). "We propose that GATA2 mRNA may be a new candidate for inclusion in a multi-marker biomarker test to detect those who will go on to develop preeclampsia." (PMID 30659233, 2019). "In this report, we show that circulating mRNA levels of the endothelial transcription factor GATA2 are significantly decreased in preeclampsia; not only in established early-onset disease but also at 28 and 36 weeks’ gestation, before the development of late-onset disease." (PMID 30659233, 2019).
preeclampsia (continued). "Therefore, we set out to establish whether GATA2 mRNA is altered in placentas collected from women with established preeclampsia." (PMID 30659233, 2019). "Notably, circulating GATA2 mRNA levels at 28 weeks’ gestation (as far as 10–12 weeks preceding diagnosis for most patients) were also significantly decreased among those destined to develop preeclampsia near term (the diagnosis of the disease was made after 36 weeks’ gestation) compared to controls." (PMID 30659233, 2019). "In view of the vital role that GATA2, miR 126 and miR 221 have in maintaining endothelial cell function, combined with the knowledge that late-onset preeclampsia is a disease of dysfunctional endothelium, we sought to examine whether circulating levels are differentially expressed in preeclampsia." (PMID 30659233, 2019).
pulpitis (1 paper, 2021). Inflammation of the dental pulp. "Several transcription factors have been identified to be involved in the TF-gene regulatory network of pulpitis, including GATA2, ETS1, FOXP3, STAT1, FOS, and JUN." (PMID 33777260, 2021). "Six transcription factors (i.e., GATA2, ETS1, FOXP3, STAT1, FOS, and JUN) were identified to play pivotal roles in pulpitis." (PMID 33777260, 2021).
sarcoidosis (1 paper, 2023). Sarcoidosis is a multisystemic disorder of unknown cause characterized by the formation of immune granulomas in involved organs. "Unlike myofibroblasts and ECM fibroblasts which enriched fibroblast activation TFs, such as GLIS1 and TRPS1, only in sarcoidosis, endothelial fibroblasts showed enrichment of FLI1, a fibroblast activation suppressor TF, and GATA2, an endothelial cell TF, strictly in sarcoidosis." (PMID 37576111, 2023).